GSDMD (gasdermin D)
Diseases named in the same sentence as GSDMD in open-access papers (continued):
Sharing a sentence is not in itself a finding about the gene and the disease.
Stroke (27 papers, 2019 to 2025). Sudden impairment of blood flow to a part of the brain due to occlusion or rupture of an artery to the brain. "NLRP3 inflammasome can activate caspase-1 state to cleaved, which in turn exposes the N-terminal of GSDMD for pore formation in cell membrane and promotes secretions of IL-1β and IL-18, causing serious of outcomes in stroke." (PMID 40289983, 2025). "Consistent with this, we found GSDMD inhibition could improve the inflammatory environment of the brain and reduced inflammation-associated neuronal toxicity or death, thereby shrinking brain infarcts and improving the prognosis of stroke." (PMID 36755018, 2023). "A similar pattern was observed 5 days post-stroke (Figures 2EA–EE), with clear GSDMD colocalization with IBA1 and GFAP in brain regions near the hypoxic core." (PMID 39210936, 2024). "The goal of this research is to clarify the role of pyroptosis and necroptosis, through the key factors of these processes, GSDMD and pMLKL, in the pathophysiology of stroke and explore the approach in which NSC transplantation affects these processes." (PMID 39210936, 2024). "Two days post-stroke, GSDMD predominantly colocalized with IBA1, slightly less with GFAP, and almost none with NEUN." (PMID 39210936, 2024). "Our demonstration that this also directly impacts the bacterial burden in the lungs of stroke mice makes GSDMD a prime target for innovative immunoprotective treatments in sterile inflammation." (PMID 39195931, 2024). "Analysis of GSDMD immunohistochemistry signal intensity and coverage revealed increased cell presence 2 days post-stroke." (PMID 39210936, 2024). "We showed that despite gene upregulation in treated groups, transplanted NSCs can reduce activity of GSDMD, predominantly in astrocytes, in stroke affected mouse brain which improved animal recovery." (PMID 39210936, 2024). "Immunohistochemical analysis revealed upregulation of Gasdermin D (GSDMD) expression post-stroke, predominantly in microglia and astrocytes." (PMID 39210936, 2024). "NLRP1 is predominantly expressed in neuronal cells after stroke and, owing to its unique pyrin structural domain, can bind directly to procaspase-1, thereby facilitating Caspase-1 cleavage of GSDMD with the pro-inflammatory factor IL-1." (PMID 37165005, 2023). "When stroke occurs, GSDMD is activated, leading to the formation of pores in cell and organelle membranes and triggering cytokine release, oxidative stress, calcium overload, endoplasmic reticulum stress, and mitochondrial dysfunction." (PMID 36755018, 2023). "The present study also revealed the downregulation of the toll-like receptor (TLR) signaling pathway, TNF signaling pathway and NOD-like receptor (NLR) signaling pathway in CD11b+ cells from GSDMD−/− mice with stroke." (PMID 36755018, 2023). "TUNEL positive cells were mainly located in the infarcted core, while GSDMD positive cells were more distributed in the peri-infarcted area at the 7th day post-stroke." (PMID 35690810, 2022). "Gasdermin D-executing pyroptosis mediated by NLRP3 inflammasomes has been recognized as a key pathogenesis during stroke." (PMID 36138981, 2022). "Conclusively, we showed that the receptors of NLRP3, NLRC4, and AIM2, the executors of Caspase-1 and−11 were the main contributors of-post stroke inflammasome activation, which participated in the production of IL-1β, IL-18, and GSDMD." (PMID 33967935, 2021). "As expected, MCAO significantly induced the expression of the cleaved GSDMD (GSDMD-N) 21 days after stroke." (PMID 34630845, 2021). "After cerebral pyroptosis was confirmed in microglia post stroke induction, we next investigated the precise role of GSDMD in stroke-induced microglia." (PMID 33329317, 2020). "Consistently, double immunofluorescence results implied that more GSDMD positive microglial cells were detected in the peri-infarct region of MCAO mice 3 days post-stroke compared to that in sham-operated mice, which were remarkably attenuated by R406." (PMID 31324751, 2019).
Stroke (continued). "In stroke pathology, MNPs are associated with capillary obstruction, ferroptosis through reduced ZO-1, Fe2+ accumulation, and lipid peroxides and pyroptosis activation through ASC/NLRP3/GSDMD activation." (PMID 41303677, 2025). "Therefore, the NF-κB/NLRP3/Caspase-1/GSDMD pathway is involved in cerebral ischemia-reperfusion damage after stroke." (PMID 39199474, 2024). "Furthermore, NSCs transplantation significantly reduced GSDMD presence in neurons, despite their scarcity both two- and five-days post-stroke." (PMID 39210936, 2024). "Our study showed that CX3CR1 gene deletion inhibited GSDMD protein activation after stroke." (PMID 38421089, 2024). "Taken together, these results suggest that GSDMD may be an important regulatory factor for restricting inflammation after stroke." (PMID 36755018, 2023). "GSDMD mediated cell pyroptosis and promoted neuroinflammation in many nervous system diseases, including Parkinson’s Disease (PD), Multiple Sclerosis (MS), spinal cord injury, stroke, Traumatic Brain injury (TBI) and Zika virus-induced brain atrophy." (PMID 34721422, 2021). "Furthermore, curcumin significantly reduced the number of gasdermin D+ (GSDMD+) Iba1+ and caspase-1+Iba1+ microglia/macrophage 21 days after stroke." (PMID 34630845, 2021). "Herein, this report provides strong evidence for the activation and formation of pyroptosis following stroke, the effector molecular GSDMD along with the caspase‐1 immunoreactivity accumulated on the plasma membrane, forming a distinctive “ring of fire” morphology in the ischemic brain." (PMID 32239625, 2020). "Additionally, immunofluorescent staining of GSDMD, caspase‐1, and IL‐1β with Iba‐1 generated another line of evidence for enhanced microglial pyroptosis following stroke, whereas A151 treatment significantly suppressed such an increase." (PMID 32239625, 2020). "GSDMD is the last downstream substrate of the pyroptosis pathway and has the closest relationship with pyroptotic cell death; therefore, targeted inhibition of GSDMD may be a viable option for the treatment of stroke." (PMID 37165005, 2023). "To determine whether neuronal death was caused by pyroptosis, which is characterized by swelling, membrane pore formation, and the secretion of proinflammatory cytokines, we analyzed GSDMD (a pore-forming protein) as a pyroptosis marker in the cortex of rats with stroke." (PMID 34740380, 2021). "Indeed, in this study, the expressions of GSDMD and GSDMD-N were drastically upregulated in microglia and more pores were detected on microglia membrane following ischemic stroke, indicating that pyroptosis occurs within microglia post-stroke." (PMID 31324751, 2019). "Stroke can trigger pyroptosis of microglia, astrocytes, neurons and BMECs (brain microvascular endothelial cells), which is mainly regulated by GSDMD (gasdermin D)." (PMID 37165005, 2023). "To explore the spatiotemporal patterns of pyroptosis and apoptosis following stroke, we performed TUNEL staining and GSDMD, ASC staining before (D0) and 1 (D1), 3 (D3), 5 (D5) and 7 days (D7) after cerebral ischemia, respectively." (PMID 35690810, 2022). "Post-stroke inflammasome activation, especially NLRP3, cleaved Caspase-1, cleaved Caspase-11, IL-1β, IL-18, and GSDMD, peaked at 3–5 days and declined at 7 days with the participation of multiple components in mice." (PMID 33967935, 2021). "Moreover, other studies suggested that GSDMD might be a promising target for stroke therapy." (PMID 34721422, 2021). "GSDMD, the pyroptosis executioner, was also predominantly expressed in microglia/macrophages, indicating that NLRP3 inflammasome‐mediated pyroptosis was mainly localized to microglia/macrophages after stroke." (PMID 39467260, 2025). "Two days post-stroke with no treatment (Group B), GSDMD-positive cells were prominently present in penumbra region near the hypoxic core, with a majority co-expressing IBA1 or GFAP, indicating expression in both microglia and astrocytes (Figures 2DA–DE)." (PMID 39210936, 2024).
Stroke (continued). "Contralateral hemisphere analysis showed fewer and less intense GSDMD-positive cells compared to the stroke-affected hemisphere (data not shown)." (PMID 39210936, 2024). "In our study, we demonstrated that hypoxanthine induces GSDME-dependent pyroptosis in endothelial cells directly rather than through GSDMD activation, providing deeper insight into why hypoxanthine plays a harmful role after stroke." (PMID 39346547, 2024). "Moreover, the investigation of GSDMD and pMLKL expression and localization following NSC transplantation in stroke-affected mice aims to provide new insights into the mechanisms by which NSCs achieve their neuroprotective advantages and prospective treatment approaches." (PMID 39210936, 2024). "However, GSDMD induces NETs (neutrophil extracellular traps) but not pyroptosis in neutrophils after stroke." (PMID 37165005, 2023). "Twenty-eight days after stroke, the mNSS scores of the gsdmd−/− group and WT group were 3.75 ± 0.4523 and 6.25 ± 0.6216, respectively (P < 0.001), indicating that the absence of GSDMD significantly promoted neurological recovery from I/R injury." (PMID 33329317, 2020). "To further examined the molecular mechanisms of neutrophil suppression after stroke in the absence of GSDMD, we performed RNA sequencing of isolated CD11b+ cells in blood from WT and GSDMD−/− mice 1 day after MCAO." (PMID 36755018, 2023).
glioma (25 papers, 2021 to 2025). A benign or malignant brain and spinal cord tumor that arises from glial cells (astrocytes, oligodendrocytes, ependymal cells). "GSDMD is a novel biomarker for evaluating the cancer prognosis because of the high protein expression level in glioma and its association with significant survival of GBM patients." (PMID 36699618, 2023). "GSDMD expression had a positive association with TMB scores in patients with glioma (p < 0.0001) and LGG (p = 0.001)." (PMID 37371484, 2023). "We found that GSDMD expression is related to genetic mutations in glioma, and highly expressed GSDMD indicated a pro-tumor immune microenvironment with more infiltrated CAFs and macrophages." (PMID 37371484, 2023). "Then we used we single-cell sequencing datasets from the TISCH database and found that GSDMD was closely associated with infiltration of monocyte/macrophage in gliomas." (PMID 34830775, 2021). "High levels of GSDMD expression are linked to shorter OS for patients with glioma (p < 0.0001)." (PMID 37371484, 2023). "Furthermore, the results of single-cell data in 10 glioma tissues confirmed the positive association among GSDMD expression, CAFs, and macrophages." (PMID 37371484, 2023). "Our results gave a hint that GSDMD might be novel maker associated with macrophage infiltration in glioma." (PMID 34830775, 2021). "GSDMD is a novel oncogene in glioma and strongly associated with tumor malignancy." (PMID 34830775, 2021). "GSDMD, a key effector protein of pyroptosis, is often overexpressed in gliomas, with its expression levels increasing in parallel with the WHO grading of gliomas and negatively correlating with prognosis." (PMID 39949740, 2025). "In contrast, elevated GSDMD expression correlated with worse prognosis in adrenal cortex carcinoma, low grade glioma, renal cancer and uveal melanoma." (PMID 39224600, 2024). "These PRGs, which are upregulated in gliomas, include caspase-3 and caspase-9, n-terminally truncated gasdermin D (GSDMD), and the inflammasome proteins NLRP2 (“NLR family pyrin domain containing 2”) and NLRC4 (“NLR family CARD domain containing 4”)." (PMID 39062119, 2024). "In this study, we constructed GSDMD knockdown U87 and A172 glioma cells, and the functional experiment results showed GSDMD knockdown inhibited the proliferation and migration of glioma cells in vitro." (PMID 37371484, 2023). "Because B cells and CD4+ T cells usually inhibit tumor growth while CAFs and macrophages promote tumor growth, it was concluded that high levels of GSDMD induced an immunosuppressive microenvironment and promoted glioma progression." (PMID 37371484, 2023). "The results A) showed that the GSDMD methylation profile in glioma was lower than that of the control subjects (p = 0.215)." (PMID 37371484, 2023). "In this study, we found that GSDMD played an oncogenic role in glioma and can be used as an independent prognostic factor." (PMID 37371484, 2023). "Consistent with the results in the TCGA cohort, GSDMD had a higher expression level in glioma tissues compared to the normal control (p = 0.030), and patients with high levels of GSDMD had shorter OS (p < 0.0001) in the GSE16011 cohort." (PMID 37371484, 2023). "Patients with glioma and higher GSDMD levels had shorter overall survival, and the Cox regression analysis revealed that GSDMD was an independent risk factor." (PMID 37371484, 2023). "To further verify the effects of GSDMD on glioma, we used NC and si-GSDMD tumor-bearing nude mice, and five mice were used in each group." (PMID 37371484, 2023). "To further explore the correlation among GSDMD, CAFs, and macrophages in glioma, we performed a single-cell analysis on 10 untreated glioma samples." (PMID 37371484, 2023). "Then, the expression levels of GSDMD were detected and the results showed significantly lower expression in U87 and A172 glioma cells treated with si-GSDMD, which was also confirmed by the WB assay." (PMID 37371484, 2023).
glioma (continued). "Then, we selected GSDMD from these five PRGs for knockdown and found that GSDMD participated in mediating the process of pyroptosis in gliomas." (PMID 36861130, 2023). "Herein, we not only identified GSDMD as a prognostic biomarker for patients with glioma but also revealed the significant effects of GSDMD on remodeling the tumor immune microenvironment." (PMID 37371484, 2023). "There is additional evidence from a computational analysis that GSDMD is significantly positively correlated with glioma malignancies." (PMID 37723542, 2023). "The transcriptional level of GSDMD in gliomas increased according to the WHO grade, and it was verified as a prognostic marker through survival analysis, Cox-regression analysis, and histological staining." (PMID 37723542, 2023). "To further verify the cancer-promoting effects of GSDMD on glioma, we evaluated GSDMD levels and correlation with prognosis in patients with glioma in another cohort from GEO (GSE16011)." (PMID 37371484, 2023). "In patients with glioma, highly expressed GSDMD was negatively correlated with B cell (p < 0.0001) and CD4+ T cell (p < 0.0001) infiltrations and positively correlated with cancer-associated fibroblasts (CAFs) (p < 0.0001) and macrophages (p < 0.0001)." (PMID 37371484, 2023). "The expression levels of GSDMD are significantly upregulated in the glioma tissues compared to the normal control group (p < 0.0001)." (PMID 37371484, 2023). "In this study, we found that the expression of GSDMD in glioma tissues is significantly higher than that in the corresponding control tissues both at mRNA and protein levels." (PMID 37371484, 2023). "We combined all tumor expression data from TCGA with GEPIA2 data and obtained differentially expressed genes that were correlated with CASP4 expression in gliomas, including GSDMD, CASP1, IL-18, and TLR2." (PMID 36713560, 2022). "Our study shows that GSDMC, GSDMD, and PJVK have transcriptional heterogeneity and are associated with glioma prognosis." (PMID 35784306, 2022). "A recent study showed that high GSDMD expression is associated with IDH-wildtype and WHO grade IV gliomas as well as shorter OS and is a response marker for TMZ treatment in glioma." (PMID 35784306, 2022). "Further analysis revealed that glioma tissues with high GSDMD expression had abundant macrophage cell (CD68+/CD163+ double positive) infiltration by using IF staining." (PMID 34830775, 2021). "This study, for the first time, found that GSDMD was overexpressed in glioma and increased significantly as glioma grade developed." (PMID 34830775, 2021). "Simultaneously, IHC analysis showed that GSDMD expression was significantly higher in glioma tissues and correlated with higher glioma WHO grade." (PMID 34830775, 2021). "GBM expressed significantly higher levels of GSDMD mRNA than LGG, suggesting that GSDMD expression increased progressively with higher glioma grade in CGGA, TCGA, Gravendeel and Rembrandt." (PMID 34830775, 2021). "In this study, we found for the first time that GSDMD expression was significantly elevated in glioma tissues and elevated as glioma grade increased both in four public datasets and in-house validation using WB and IHC staining." (PMID 34830775, 2021). "For the first time, this study elaborated the prognostic role and TMZ-treatment response marker of GSDMD in glioma." (PMID 34830775, 2021). "We found that glioma patients with high GSMDA, GSDMD and GSDME expression were all associated with shorter overall survival time." (PMID 34830775, 2021). "Our results showed that high GSDMD expression in glioma patients who received chemotherapy predicted favor prognosis in CGGA dataset." (PMID 34830775, 2021). "GSDMD expression in glioma significantly correlated with clinical parameters, such as IDH1/2 wildtype, 1p19q non-co-deletion and mesenchymal subtype." (PMID 34830775, 2021).